CAPN7 (calpain 7)
Description:
Calcium-regulated non-lysosomal thiol-protease.
Synonyms: PalBH; CALPAIN7
Tractability: PROTAC: ubiquitination databases record sites on it; its protein half-life has been measured.
Gene: Protein-coding gene on chromosome 3 (15,206,112 to 15,252,919, forward strand). Ensembl gene ENSG00000131375.
Subcellular location: Nucleus
Subcellular location (Human Protein Atlas): Cytosol; Centrosome
Pathways (Reactome):
Extracellular matrix organization: Degradation of the extracellular matrix
Gene Ontology:
Molecular function: endopeptidase activity; MIT domain binding; protein binding; cysteine-type endopeptidase activity; calcium-dependent cysteine-type endopeptidase activity
Biological process: positive regulation of epithelial cell migration; self proteolysis; proteolysis
Cellular component: extracellular exosome; nucleus
Genetic constraint (gnomAD): Loss-of-function variants: 29 observed, 44.84 expected, observed/expected ratio (o/e) 0.65, 90% interval 0.48 to 0.88. The upper end of that interval is the gene's LOEUF score, 0.88, which puts it in group 3 of 6, group 1 being the genes least tolerant of losing a copy. Missense variants: 453 observed, 454.53 expected, observed/expected ratio (o/e) 1, 90% interval 0.92 to 1.08. Synonymous variants: 168 observed, 154.42 expected, observed/expected ratio (o/e) 1.09, 90% interval 0.96 to 1.24.
Homologues: Orthologues: chimpanzee CAPN7 (99% identical), macaque CAPN7 (99% identical), dog CAPN7 (97% identical), rabbit CAPN7 (96% identical), guinea pig CAPN7 (96% identical), pig CAPN7 (96% identical), rat Capn7 (95% identical), mouse Capn7 (95% identical), tropical clawed frog capn7 (81% identical), zebrafish capn7 (77% identical), Caenorhabditis elegans clp-2 (41% identical). Paralogues in human: CAPN1 (21% identical), CAPN8 (21% identical), CAPN2 (20% identical), CAPN3 (19% identical), CAPN9 (19% identical), CAPN14 (18% identical), CAPN11 (18% identical), CAPN13 (17% identical), CAPN12 (17% identical), CAPN6 (15% identical), CAPN15 (15% identical), CAPN5 (15% identical), and 8 more.
Diseases named in the same sentence as CAPN7 in open-access papers:
CAPN7 is named in the same sentence as 9 diseases in open-access papers, as found by Europe PMC text mining. Sharing a sentence is not in itself a finding about the gene and the disease. The quoted sentences say what the papers report.
embryonal carcinoma (2 papers, 2022 to 2025). A non-seminomatous malignant germ cell tumor characterized by the presence of large germ cells with abundant cytoplasm resembling epithelial cells, geographic necrosis, high mitotic activity, and pseudoglandular and pseudopapillary structures formation. "A recent analysis of the Cancer Genome Atlas demonstrated that KIT, KRAS, and NRAS gene variants were observed only in seminoma, while gene variants in B3GNT8, CAPN7, FAT4, GRK1, TACC2, and TRAM1L1 occurred only in embryonal carcinoma." (PMID 41426877, 2025). "Mutations in ADAMTS20, ARHGAP10, OR1L4, PDS5A, and RPLP0 were only found in mixed germ cell tumors, while mutations in B3GNT8, CAPN7, FAT4, GRK1, TACC2 and TRAM1L1 were only observed in embryonal carcinoma, and their mutation frequency was around 2%." (PMID 36713456, 2022). "As described in our results, mutation that only occurs in embryonal carcinoma (B3GNT8, CAPN7, FAT4, GRK1, TACC2 and TRAM1L1) or seminoma (KIT, KARS and NRAS) may be valuable molecular markers and therapeutic targets that need to be considered clinically." (PMID 36713456, 2022). "Differences in somatic mutations between subtypes are also of concern, with our results suggesting that mutations in some genes (B3GNT8, CAPN7, FAT4, GRK1, TACC2, and TRAM1L1) occur only in embryonal carcinoma, while mutations in KIT, KARS, and NRAS are observed only in seminoma." (PMID 36713456, 2022).
endometriosis (2 papers, 2023 to 2025). The growth of functional endometrial tissue in anatomic sites outside the uterine body. "On the other hand, another study reported an increased expression of CAPN7 in the eutopic endometrium and endometrial stromal cells of women diagnosed with endometriosis." (PMID 36901866, 2023). "Collectively, these studies demonstrate that reduced FOXO1 expression and the associated defective decidualization in eutopic endometrium of endometriosis patients results from multiple dysregulated pathways, including impaired Notch signaling and enhanced CAPN7 and NEK activity." (PMID 40072055, 2025).
colon cancer (1 paper, 2020). "Upregulation of LINC00657 inhibits cell viability via promoting CAPN7 expression and suppressing the PI3K/Akt pathway in colon cancer cells." (PMID 33246471, 2020). "In another study, LINC00657 overexpression was shown to increase invasive ability of colon cancer cells via targeting the PI3K/Akt pathway and CAPN7 expression." (PMID 33246471, 2020).
E. coli infection (1 paper, 2020). "E. coli infection resulted in the upregulation of the genes encoding proteases, which participate in the degradation of ECM, namely, ADAM10 (logFC of 2.62), ADAM17 (logFC of 8.75), MMP9 and MMP14 (both with a logFC of 2.58), CAPN7 and CAST (both with logFC of 2.20)." (PMID 32234079, 2020).
infertile (1 paper, 2018). "Therefore, we hypothesized that the aberrant CAPN7 expression in the eutopic endometrium of the infertile women with ENDO may cause failure of embryo implantation via degradation of HOXA10." (PMID 29459744, 2018). "Conversely, the expression of CAPN7 in the endometrium of infertile ENDO women was ~ 1.5-fold compared with the control group (p < 0.001)." (PMID 29459744, 2018).
cancer (1 paper, 2021). A tumor composed of atypical neoplastic, often pleomorphic cells that invade other tissues. "The results showed a trend of a higher expression level in cancer tissues for ISG15, CAPN7, SEMA3A, and DYRK4 genes." (PMID 35008303, 2021).
CAPN7 also shares sentences with these, for which no sentence is quoted: seminoma (2 papers); tumor (2); mixed germ cell tumor (1).